FN1 (fibronectin 1)
Diseases named in the same sentence as FN1 in open-access papers (continued):
Sharing a sentence is not in itself a finding about the gene and the disease.
breast carcinoma (continued). "Several of these genes are described in breast cancer including FN1, Fibronectin1, which is down-regulated in high HER2 expressing cell lines, and has been reported to be suppressed in metastatic breast cancer." (PMID 25428913, 2015). "The results of the present study indicated that the FN1 gene was upregulated in the development of breast cancer and that FN1 was a hub protein with a degree score of 39 in the established PPI network." (PMID 25824986, 2015). "KLF6-SV1, one of these splice variants, is able to drive breast cancer cells into an EMT-like phenotype, with loss of CDH1 and increased expression of CDH2 and FN1." (PMID 24429391, 2014). "FN1 is a protein present in the extracellular matrix that is a candidate serum biomarker for detecting breast cancer, and disrupting the interaction between FN1 and integrins in breast cancer cells led to increased apoptosis and response to radiation." (PMID 23758962, 2013). "Our results have shown the expressional association and clinical relevance of six genes (CDH2, FN1, CITED2, CTNNB1, and CTNNA3) together with GRHL2 for breast cancer metastases." (PMID 23441166, 2013). "Collagen I again features in this prometastatic signature, alongside COLV and COLVI; importantly, COLVI has also been associated with a functional role in TNBC metastasis in a cell-derived matrix model, while COL1A1 or FN1 alone can also drive an aggressive breast cancer phenotype in culture models." (PMID 38791926, 2024). "Furthermore, FN1/PI3K/Akt signaling contributes to breast cancer cell resistance against docetaxel by inhibiting the ASK1/p38 apoptotic pathway." (PMID 38818409, 2024). "Upregulated FN1 expression correlates with poor prognosis in breast cancer." (PMID 39769169, 2024). "It reveals that miR-33b-3p may influence breast cancer progression by regulating the important ECM component FN1, providing a new direction for breast cancer therapy." (PMID 39684583, 2024). "In breast cancer models, UGDH knockdown caused increased CDH1 and FN1 expression." (PMID 37858159, 2023). "Interestingly, we observed that one set of proteins was identified more frequently, with HLA-A, HLA-B, A2M, ACTB, ALDOA, ANXA2, and FN1 identified in at least 13 of 22 studies that explored the vesicular proteome in breast cancer." (PMID 37629204, 2023). "Silencing of FN1 impairs the proliferation and invasive ability of breast cancer cells, suggesting that FN1 may serve as a prognostic marker and therapeutic target for breast cancer." (PMID 38063927, 2023). "Two additional genes, KRR1 and FN1, were only detected in the breast cancer-specific analysis." (PMID 37173324, 2023). "Moreover, the upregulation of FN1, CDH2, and VIM is commonly associated with the epithelial–mesenchymal transition (EMT) in breast cancer and also in mammary epithelial cells." (PMID 36013233, 2022). "FN1 is an ECM protein that interacts with integrin and other ECM proteins such as collagens and its elevated expression is associated with an invasive and metastatic breast cancer phenotype 39." (PMID 34976221, 2022). "Similarly, lung alveolar epithelial cells have been reported to induce Src-mediated Secreted frizzled-related protein 2 (SFRP2) in breast cancer cells promoting FN1 fibril formation and cancer cell survival." (PMID 33731188, 2021). "However, we found support in the literature for the involvement of the selected highly central genes (COPS5, FN1, and CUL3) in breast cancer susceptibility (Sections 3.3, 3.6, and 3.8)." (PMID 33735170, 2021). "FN1 might also be a potential biomarker for radioresistance in head and neck squamous cell carcinoma and a potential therapeutic target for breast cancer." (PMID 33439992, 2021). "It remained unclear though, whether extracellular MMP2, CTGF and FN1 facilitate invasion in breast cancer interdependently." (PMID 33087801, 2020).
breast carcinoma (continued). "FN1 (fibronectin 1) acts as a ceRNA for miR-200c in the canonical SNAIL-ZEB-miR200 pathway in breast cancer cells, whereas TGFBI (transforming growth factor-beta-induced) is a transcript that is highly induced during EMT in lung cancer cells, which acts as the ceRNA for miR-21 to modulate EMT." (PMID 31947678, 2020). "EMT transition can be induced by FN1 in human breast cancer MCF7 cells." (PMID 32787954, 2020). "Oncomine analyses of COL1A1 and FN1 in different human breast cancer datasets suggest that these two genes may be promising targets for the future studies." (PMID 30237810, 2018). "In addition, ARRDC3, which is a tumor suppressor and involved in integrin trafficking, was upregulated in breast cancer, whereas FN1 was downregulated after liprin-α1 knockdown." (PMID 30005669, 2018). "Similarly to COL1A1, FN1 was also highly expressed in breast cancer and the advanced N1+ stage of breast cancer compared with their control groups." (PMID 30237810, 2018). "In addition, silencing Col4A1 or FN1 in breast cancer cells represses malignant phenotypes in 3D cultures." (PMID 26682273, 2015). "Similarly, we chose RHOA, MKI67, CITED2, ACTA2, FN1 and TGFB3, as all have been implicated in EMT and highly metastatic breast cancer." (PMID 23441166, 2013). "Finally, proteins highly correlating with both simple and complex carcinoma were mainly related to pathways including ECM organisation, cell adhesion, cell motility, and cell migration, including ECM-associated proteins previously associated with mammary cancer, such as BGN and FN1." (PMID 39462388, 2024). "Also, as a tumor suppressor, miR-429 could inhibit the activation of the Wnt/β-catenin signaling pathway by targeting HOXA9 in osteosarcoma and FN1 in breast cancer." (PMID 38002073, 2023). "The elevated FN1 expression may also promote the occurrence of cancer, including breast cancer." (PMID 34456964, 2021). "Thus, FN1 might create a suitable microenvironment that is conducive to distant metastasis of breast cancer." (PMID 32489334, 2020). "Furthermore, high CAP1 expression was associated with poor tumor characteristics and correlated with expression of genes and biological pathways within growth promoting (such as Abl, RRAGC and mTOR) and cell motility processes (e.g., Arp2/3 complex, ARSB and FN1) in breast cancer." (PMID 30524378, 2018). "Similarly, we expanded the breast cancer input layer with the hyaluronan-mediated motility receptor (HMMR) connected to FN1; the TGFBR connected to SNAI1 and SNAI2; the interLeukin 1 receptor type I (IL1R1) and the thyroid hormone receptor beta (THRB) connected to TRAF1 and MYC, respectively." (PMID 28775339, 2017). "Therefore, the FN1 gene was found to be a key regulator in breast cancer development." (PMID 25824986, 2015). "Established markers for breast cancer cells (BRCA1, MAP3K1, BMPR1A) and fibroblasts (FN1, VIM, COL6A2) were used to classify the clusters." (PMID 39805002, 2025). "Worthy, the signature demonstrated to predict poor outcomes in breast cancer patients exhibiting high transcriptional levels of ITGA11, THBS1, FN1, EMP1, ITGA2, FYN, SPP1, and EMP2." (PMID 38937754, 2024). "Both FN1 and BGN correlate positively in a transcriptomic study between canine mammary carcinomas and human breast cancer." (PMID 39462388, 2024). "The bone marrow also expresses high levels of FN1, and this environment appears to induce ITGB3 upregulation in metastasized breast cancer cells." (PMID 39707454, 2024). "miR-200b targeted fibronectin 1 (FN1) and suppressed EMT phenotypes to overcome doxorubicin resistance in breast cancer cells." (PMID 35682560, 2022). "The result showed that the protein expression of TUBB3, MCM2, FN1, S100A7, and TFF1 was increased, and the protein expression of MYOC was downregulated in luminal A breast cancer, which was consistent with the result of RNA expression." (PMID 35692369, 2022).
breast carcinoma (continued). "In conclusion, FGFR2, RET, ERBB4, MMP16, FN1, and SOX2 are potential targets of HON for overcoming TAM resistance in breast cancer." (PMID 36601474, 2022). "Six target genes (FGFR2, RET, ERBB4, SOX2, FN1, and MMP16) were analyzed across breast cancer studies using the cBioPortal to assess genomic alterations." (PMID 36601474, 2022). "We also observed upregulation of FN1, PLAU and ALCAM in patients at most stages of breast cancer compared to expression in healthy individuals." (PMID 34641959, 2021). "We found that FN1, PLAU and ALCAM were upregulated in patients with most subtypes of breast cancer compared to expression in healthy volunteers." (PMID 34641959, 2021). "PTK7 expression in breast cancer was significantly positively correlated with COL1A1, FN1, WNT5B, MMP11, MMP14 and SDC1 in breast cancer." (PMID 34367983, 2021). "When evaluated in clinical datasets, overexpression of FN1, PLAU, and ALCAM was observed in patients with different subtypes of breast cancer." (PMID 34641959, 2021). "When evaluated in a clinical cohort, we observed significant increase in expression of FN1, PLAU and ALCAM in patients with most subtypes of breast cancer compared to healthy volunteers." (PMID 34641959, 2021). "Higher mRNA expression was detected in FN1 and LTBP1 in breast cancers than normal population, with increasing expression levels from primary to metastatic cancers, whereas ATF3 had reversed expression patterns." (PMID 33500735, 2021). "We then examined gene expression from 9 different breast cancer datasets and found correlation between HIF1A and LOX, ITGA5, and FN1 mRNAs, supporting the upstream regulatory role of HIF1A in their transcription." (PMID 32415208, 2020). "FN1 and BGN were targeted here due to their expression pattern being similarly up-regulated in human breast cancers." (PMID 30205506, 2018). "However, no study on COL1A1 and FN1 associations with breast cancer has been reported." (PMID 30237810, 2018). "If hsa-miR-96 directly interacts with C1QTNF6, FN1, and TFGB1 in breast cancer, the expression level of mRNAs should be down-regulated because the overexpressed hsa-miR-96 will suppress the mRNA’s expression." (PMID 28793339, 2017). "Analysis using the Oncomine research tool revealed that mRNA levels of Fibronectin (FN1) and VEGFA are significantly elevated in the tumor and stromal compartments of breast carcinomas." (PMID 28977919, 2017). "We found that the mean transcript expression of VIM, CDH2, FN1, and TWIST1 were higher in the basal B breast cancer cells with low FRK transcript levels as compared to Basal A and Luminal cells that harbor high FRK transcript levels (P<0.05)." (PMID 29348886, 2017). "Training on public gene expression profiles of 995 breast cancer patients, this method prioritized one gene-set pair (GRHL2, CDH2, FN1, CITED2, MKI67 versus CTNNB1 and CTNNA3) from all 2717 possible gene-set pairs (GSPs)." (PMID 23441166, 2013). "We took as «baits» five bimodal genes reported as important breast cancer genetic markers - ERBB2, ESR1, PLAUR, FN1, and STAT1, and calculated the "close neighbor" gene groups that were synchronously expressed with each of them in the Sorlie295 set." (PMID 20158879, 2010). "Using this methodology, we identified nine proteins—FN1, VWF, PRG4, MMP9, CLU, PRDX6, PPBP (CXCL7), APOC1, and CHL1—that were robustly quantified in serum and showed statistically significant differences between breast cancer patients and healthy controls." (PMID 40940928, 2025). "Notably, FN1 and COL1A1, all regulated by TGFβ, exhibit coordinated expression in breast cancer lymph node metastases." (PMID 41231242, 2025). "FN1 was reported to mediate the activation of aspartate metabolism and promote the progression of triple‐negative and luminal a breast cancer." (PMID 40638546, 2025). "Although there is currently no direct literature reporting it, it is highly likely that FN1 influences breast cancer cell activity through its effects on the ECM." (PMID 39684583, 2024).
breast carcinoma (continued). "For example, a resent study reported that silencing FN1 inhibits YAP1/Hippo pathway activation by enhancing YAP1 phosphorylation, reduces aspartate uptake and utilization via SLC1A3, and suppresses breast cancer cell proliferation, invasion, migration and promotes apoptosis." (PMID 39218967, 2024). "Carcinoma EVs shared 60 over-represented proteins, including ECM proteins involved in cell adhesion, motility, wound healing and maintenance of cell shape (FN1, BGN, HAPLN1), which have all been previously identified in human breast cancer and canine mammary cancer studies." (PMID 39462388, 2024). "Additionally, stromal FN1 promotes both FAK/RAS/MEK/ERK and FAK/PI3K/Akt pathways in breast cancer cells, leading to estrogen receptor-α phosphorylation and subsequent tamoxifen sensitivity." (PMID 38818409, 2024). "Additionally, FN1 which is an ECM remodeling-related molecule was downregulated in the NRP-1 KO cells and was shown to play a key role in breast cancer stroma invasion and metastasis." (PMID 37175499, 2023). "Further that the results of LD and haplotype study revealed the relationship between FN1 (key gene in breast cancer) with endometriosis, therefore FDA approved drugs used in breast cancer and endometriosis were selected for validation of the biomarkers using docking procedure by Autodock vina." (PMID 37607964, 2023). "The protein expression results of TUBB3, MCM2, MYOC, FN1, S100A7, and TFF1 were consistent with the mRNA expression result COL10A1, LEP, PLIN1, PGM5-AS1, and TRHDE-AD1 were capable of discriminating luminal A breast cancer and normal controls." (PMID 35692369, 2022). "We also analyzed the relationship between the mRNA levels of FGFR2, ERBB4, RET, FN1, MMP16, and SOX2 and tumor stages in breast cancer using GEPIA and found that the levels of FGFR2 were significantly upregulated in stage I and remained stable across stages II–X." (PMID 36601474, 2022). "The FN1 sub-networks for MDA-MB-231 and MCF-7 revealed functional links through which overexpression of FN1 possibly promotes EMT and adhesion in breast cancer cells." (PMID 34641959, 2021). "Kaplan–Meier curves of relapse-free survival times of breast cancer patients with lymph node positive status, stratified by FN1, and PLAU expression levels, demonstrate that expression changes obtained from our bioreactor system recapitulate clinical breast cancer gene expression profiles." (PMID 34641959, 2021). "Integrin α5β1 is a well-known major receptor for FN1 and was demonstrated to bind to its receptor integrin α5β1 activating the PI3K/Akt signaling pathway, thus, promoting the progression of breast cancers." (PMID 34901156, 2021). "Moreover, although the increased FN1 expression which followed with the activite of p-Akt1 had observed in this study, however, the opposite role of p-Akt1 on regulating FN1 expression also reported in breast cancer cells, the interaction between FN1 and p-Akt1 may be have a more complex manner." (PMID 34758823, 2021). "Co-expression analysis and gain- or loss-of-function of PTK7 in TNBC cell lines revealed that PTK7 participates in EGFR/Akt signaling regulation and associated with extracellular matrix organization and migration genes in breast cancer, including COL1A1, FN1, WNT5B, MMP11, MMP14 and SDC1." (PMID 34367983, 2021). "Due to overexpression of FN1 in most flow-exposed cells and its roles in EMT and cell adhesion, we analyzed its interaction sub-network to better understand how flow exposure potentially affects metastatic events in breast cancer cells." (PMID 34641959, 2021). "It has been reported that the abnormal expression of STAT1, ESR1, CYP1B1, FN1 and UGT1A family genes is closely related to breast cancer and TAM multidrug resistance, while the relationship between AKR1 family and breast cancer and TAM resistance has not been studied." (PMID 34886806, 2021).
breast carcinoma (continued). "Furthermore, we propose that CTGF is a versatile regulator in breast cancer and facilitates SPARC, LOX, ZEB1, VIM and FN1 expression changes." (PMID 33087801, 2020). "In view of the numerous studies demonstrating overexpression of EDB/EDA− FN1 in tumorigenic ECM, it can be speculated that it may also be upregulated in our TGF-β-treated and drug-resistant breast cancer cells." (PMID 32756405, 2020). "Future work may focus on characterizing how chromatin looping of FN1 and CD9 functionally and mechanistically contributes to ERα + breast cancer resistant to the endocrine therapy." (PMID 32787954, 2020). "The pronounced secretion of TGFβ1 by CAFs in breast cancer promotes an aggressive phenotype in tumor cells also through direct activation of EMT, with decreased expression of E-CADHERIN and over-expression of VIMENTIN, Fibronectin1 (FN1), MMP2 and MMP9." (PMID 30927908, 2019). "In breast cancer cells, GSEA data analysis revealed liprin-α1 in the regulation of membrane microdomains (including TGFRB2), regulation of proteolysis (including SORL1, FN1) and peptidase activity and regulation of morphogenesis of epithelium." (PMID 30005669, 2018). "Thus, expression levels of p38MAPK targets FN1 and VEGFA are elevated in breast cancers and a high level of these factors is an unfavorable marker of disease recurrence and poor-outcome." (PMID 28977919, 2017). "Breast cancer Met-1 cells were transducted with a DACH1 expression vector resulting in an ∼4.5-fold increase in DACH1 expression and subsequent reduction of CSC markers CD44, KLF4 and MYC as well as EMT markers including FN1 and VIM by mRNA analysis." (PMID 28659634, 2017). "The present study suggested that FN1, IL6 and FOS may be potential targets in the development of treatments for breast cancer." (PMID 25824986, 2015). "Recent studies have shown several members of let-7 family were diminished expression in breast cancer compared with normal breast tissues, and inhibited the breast cancer cell migration and invasive ability through regulating HMGA2, Lin28, GAB2, FN1, MAPK and MMPs." (PMID 25884389, 2015). "We found that neither the luminal A breast cancer cell line (MCF7) or the type 1 endometrial cancer cell line (Ishikawa) express FN1 or MSN, consistent with their pre-EMT phenotype, indicated by expression of E-cadherin and lack of ZEB1." (PMID 21501518, 2011). "Interestingly, several studies have posited FN1 and ITGA3 as potential autonomous prognostic biomarkers for various diseases, including ovarian cancer, pancreatic cancer, oral squamous cell carcinoma, and breast cancer." (PMID 39114033, 2024). "Besides, seven genes including BRCA1, FN1, CCNE1, CCND1, CHEK1, BUB3, and CDC25A were identified as the hub nodes by the PPI network, and CCNE1 and CHEK1 were confirmed to be related with the prognostic survival of the patients with breast cancer." (PMID 35186236, 2022). "Several ECM genes such as FN1 were not altered during short-term μg in MCF-7 breast cancer cells." (PMID 31261642, 2019). "Therefore, the key role of FN1, IL6 and FOS in breast cancer development has been demonstrated." (PMID 25824986, 2015). "The FN1, IL6 and FOS genes may therefore be potential targets in the treatment of breast cancer." (PMID 25824986, 2015). "In addition, the FN1, IL6 and FOS genes were found to be involved in breast cancer development." (PMID 25824986, 2015). "Additionally, many markers we observed that defined our monocyte clusters (FABP5, FN1, IL1RN, CCL3, CCL4, CXCL8, CXCL3, IL1B) during transient, short-term CM stimulation, were elevated in either PD-L1pos or PD-L1neg TAMs isolated and sequenced from breast cancer." (PMID 40176808, 2025). "Therefore we could assess that FN1 does not alter invasive behavior of breast cancer cells in 3D invasion setup." (PMID 33087801, 2020).
breast carcinoma (continued). "In addition, patients with breast cancer with low mRNA levels of RET, MMP16, FN1, and SOX2 had better RFS, but this was not significant in the opposite groups (p > 0.05)." (PMID 36601474, 2022). "Moreover, patients with breast cancer having low mRNA levels of RET, MMP16, FN1, and SOX2 had better OS; however, the difference was not significant." (PMID 36601474, 2022).